EPO (erythropoietin)
Diseases named in the same sentence as EPO in open-access papers (continued):
Sharing a sentence is not in itself a finding about the gene and the disease.
Sepsis (continued). "Because inflammation and systemic infection suppress erythropoiesis in the bone marrow, this finding may suggest the effectiveness of erythropoietin administration concomitant with antimicrobial therapy to maintain appropriate HGB levels in patients with CKD who experience sepsis during admission." (PMID 35327348, 2022). "Therefore, EPO might be beneficial in survival improvement as other interventions for sepsis treatment were comparable between EPO and non-EPO groups." (PMID 34831360, 2021). "Despite erythropoietin presenting anti-apoptotic, anti-inflammatory, antioxidant, and cytoprotective effects and showing to be beneficial to neurological damage associated to malaria and sepsis, no further clinical use was described so far." (PMID 35250433, 2021). "However, the plasma hepcidin, EPO and IL-6 of sepsis patients upon ICU admission were significantly higher than those of healthy volunteers and decreased gradually throughout the study, but they remained significantly higher on day 7 than those of healthy volunteers (all P < 0.05)." (PMID 31183575, 2019). "Also, IGF1 serum levels at third week of life were significantly lower in those patients who developed bronchopulmonary dysplasia, needed any kind of mechanical ventilation or oxygen support, patent ductus arteriosus, sepsis in the first 3 weeks of life, EPO treatment or needed transfusion." (PMID 24523937, 2014). "Following the multivariate analysis erythropoietin-therapy (p < 0.0001) and intraventricular hemorrhage (IVH) (p = 0.003) were significantly associated with ROP while gestational age ≤24 weeks (p = 0.011) and sepsis (p = 0.002) were associated with the onset of P-ROP." (PMID 23837411, 2013). "In addition, the blunted endogenous EPO response in critically ill patients with sepsis may contribute further to microcirculatory dysfunction and tissue dysoxia." (PMID 17509156, 2007). "The combined FEK indicator, including Fibroblast Growth Factor 23, erythropoietin, and Klotho, predicted the development of AKI, short-/long-term mortality, and one-year CKD progression in critical care patients with sepsis." (PMID 37892163, 2023). "Except for enzymes contributing to metabolic pathways, under hypoxia, HIFs regulate several genes with central roles in sepsis, including heme oxygenase-1 (HMOX1), erythropoietin (EPO), and the vascular endothelial growth factor (VEGFA)." (PMID 37367740, 2023). "In sepsis, FGF23 expression and secretion can be induced by cytokines and by signals triggered by renal hypoxia, such as glycerol-3-phosphate and EPO." (PMID 37892163, 2023). "Erythropoietin (EPO) and uromodulin are kidney-derived molecules that influence macrophage and sepsis progression." (PMID 36012420, 2022). "Despite the damage done to the kidney in SwAKI, plasma levels of erythropoietin are known to increase in both AKI and sepsis." (PMID 35163625, 2022). "Thus, EPO may be a potential target for the treatment of patients with sepsis." (PMID 36016936, 2022). "Collectively, we found that EPO and SAL protected LPS-tolerized mice against secondary infection of E. coli–induced sepsis." (PMID 36016936, 2022). "We previously reported that EPO attenuated AKI and cardiac dysfunction in mouse models of endotoxemia and cecal ligation and puncture-induced sepsis." (PMID 36211426, 2022). "Nevertheless, EPO significantly restored the hematocrit in 5/6Nx CLP mice and attenuated sepsis severity, possibly through the improved tissue hypoxia." (PMID 34831360, 2021). "In hemorrhagic shock and sepsis-induced AKI rat model, Fgf23 gene expression is increased in bone marrow and is erythropoietin (EPO)-dependent." (PMID 30405444, 2018). "In the context of sepsis, non-survivors have been observed to exhibit elevated levels of EPO compared with survivors, with endogenous EPO concentrations correlated with indicators of tissue hypoperfusion, such as lactate and the carbon dioxide gap." (PMID 40114237, 2025).
Sepsis (continued). "Non-survivors of sepsis often exhibit higher endogenous EPO concentrations, correlating with tissue hypoperfusion." (PMID 41012526, 2025). "We hypothesized that a combined indicator that includes plasma FGF23, EPO, and Klotho would predict the development of AKI, mortality, and long-term CKD progression in sepsis patients." (PMID 37892163, 2023). "One trial that aimed to investigate the effects of EPO on the microcirculation of patients with severe sepsis was discontinued due to lack of recruitment (NCT01087450)." (PMID 36211426, 2022). "There is no clinical evidence on the beneficial or harmful effects of EPO in patients with sepsis and there is only little evidence regarding the beneficial or harmful effects of EPO in ICU patients in general." (PMID 36211426, 2022). "Findings from individual trials suggest additional maternal health benefits with MMS supplementation, such as reduced cortisol and erythropoietin levels in the third trimester, and reductions in obstetric complications such as PPROM, postpartum hemorrhage, and puerperal sepsis." (PMID 36405527, 2022). "Unfortunately, only the high dose of EPO (4000 units/kg) attenuated CLP sepsis regardless of the preconditioning renal injury." (PMID 34831360, 2021). "Hence, the increased EPO production in sepsis is, partly, a compensation for the reduced EPOR in sepsis and implies a possible influence of EPO on sepsis." (PMID 34831360, 2021). "Because of the pleiotropic effects of EPO, increased EPO production during sepsis is not only due to renal hypoxia but possibly also a response toward EPOR reduction." (PMID 34831360, 2021). "A high-dose EPO, but not a low-dose, attenuated sepsis in mouse models as determined by mortality and serum inflammatory cytokines." (PMID 34831360, 2021). "Because EPO protects several organs, including the liver, through activation of the EPO receptor/β-common receptor (EPOR/βcR) complex, the inadequate expression of EPOR during sepsis possibly reduced the protective effects of EPO." (PMID 34831360, 2021). "In patients with sepsis, non-survivors had significantly lower plasma iron, EPO and sTfR/log ferritin, but higher plasma hepcidin, ferritin and IL-6 than survivors on days 1, 3 and 7 of ICU admission." (PMID 31183575, 2019). "Plasma hepcidin, EPO and IL-6 of survivor or non-survivor patients with sepsis upon ICU admission were significantly higher than those of healthy volunteers and decreased gradually throughout the study." (PMID 31183575, 2019). "This suggests that EPO elevation in sepsis may serve as a marker of disease severity rather than a protective response." (PMID 40114237, 2025). "The aim of this study was to investigate the gene expression profile of HIF1A, ISG15, HK2, LDHA, HMOX1, EPO, and VEGFA under the setting of sepsis and septic shock, and furthermore to evaluate whether any of these molecules has potential value as a prognostic factor." (PMID 37367740, 2023). "However, spleen apoptosis of EPO-treated CLP in No Nx mice and BiNx mice was evaluated and EPO attenuated spleen apoptosis in both models, regardless of the different in the severity of sepsis." (PMID 34831360, 2021). "Due to (i) the uremia-enhanced sepsis severity, (ii) the high prevalence of sepsis with pre-existing renal injury and (iii) the non-erythropoiesis immunomodulation of erythropoietin (EPO), EPO was tested in sepsis with pre-existing renal injury models with the retrospective exploration in patients." (PMID 34831360, 2021). "Indeed, high-dose EPO, but not low-dose, improved sepsis survival in all models, except for LPS, regardless of the preconditioning kidney injury without an effect on SBP." (PMID 34831360, 2021). "Furthermore, high-dose EPO, but not low-dose, attenuated sepsis-induced renal injury in CLP with or without 5/6Nx but not in the LPS model, possibly due to the non-renal injury in the LPS model." (PMID 34831360, 2021).
Sepsis (continued). "Blunted EPO production and suppressed erythropoiesis by cytokines may be reasons for an absence of increase in sTfR in non-surviving sepsis patients despite lower plasma iron and higher RDW in comparison with those of surviving patients." (PMID 31183575, 2019). "Furthermore, a single measurement of EPO may not fully capture the dynamic changes in EPO levels during the acute phase of sepsis." (PMID 40114237, 2025). "This phenomenon may have been due (at least in part) to more severe inflammation that resulted in dominant inhibition of EPO production and worse renal function that decreased EPO production directly in non-surviving sepsis patients than surviving sepsis patients." (PMID 31183575, 2019). "EPO use did not increase the incidence of ROP, sepsis or NEC." (PMID 35356441, 2022). "Indeed, high-dose EPO (>8000 units/week), but not the low-dose EPO, showed the better sepsis outcomes including survival rate and amount of vasopressor—the greater the EPO dose, the lesser the vasopressor dependence index (VDI) due to the sepsis-induced EPO resistance." (PMID 34831360, 2021).
Cerebral ischemia (66 papers, 2008 to 2024). Restriction of arterial blood supply to the brain associated with insufficient oxygenation to support the metabolic requirements of the tissue. "Although the presence of functional EPO receptors in neurons has been challenged, EPO selectively reduced inflammatory and oxidative stress processes associated with brain ischemia, and prevented neuronal apoptosis." (PMID 22759774, 2012). "The intracerebral injection of recombinant human erythropoietin in either transient forebrain ischemia or regional brain ischemia causes neuroprotection." (PMID 21766022, 2011). "In animal models, a neuroprotective effect is associated with EPO activity in the brain, and EPO reduces neuronal cell death and inflammation associated with brain ischemia, with a decrease in astrocyte activation, recruitment of microglia, and proinflammatory cytokine production." (PMID 33330462, 2020). "Thus, the aim of this study was to investigate the protective effect of FA on nerve injury induced by cerebral ischemia and whether the cerebroprotective effect of FA is associated with EPO and G-CSF induction in the rat brain." (PMID 25667662, 2015). "Our previous study investigated the neuroprotective effects of EPO by shifting microglial polarization and inhibiting excessive gliogenesis after cerebral ischemia in mice." (PMID 35715965, 2022). "Experimental administration of exogenous EPO revealed amelioration of neuronal impairments related to several disease conditions, such as cerebral ischemia, intracerebral hemorrhage, and traumatic brain injury." (PMID 35897720, 2022). "Recent studies have demonstrated that EPO elicited beneficial effects in cerebral ischemia, especially in preventing ischemic neuronal injury." (PMID 35250554, 2022). "Previous research has revealed the combined use of mesenchymal stem cells and recombinant human erythropoietin (EPO) for treating cerebral ischemia increased cell proliferation and neurogenesis." (PMID 35270042, 2022). "Recombinant human erythropoietin (rhEPO) has been shown to exert anti-apoptotic and anti-inflammatory effects after cerebral ischemia." (PMID 35813499, 2022). "In the current study, GHI was found to upregulate brain EPO and iNOS expression in rats with cerebral ischemia injury." (PMID 34539402, 2021). "Erythropoietin (EPO) also has potential therapeutic use, in terms of neuroprotection, as studies have demonstrated that EPO can improve white integrity after cerebral ischemia." (PMID 33532143, 2021). "Here, neuroprotective and antiedematous action of erythropoietin has been linked with the preservation of AQP4 function in trauma, hydrocephalus, and cerebral ischemia." (PMID 34966347, 2021). "Previous studies have indicated that HIF-1α inhibits neuronal apoptosis following cerebral ischemia in rats by upregulating EPO." (PMID 34288817, 2021). "Conversely, the activation of the Jak2 signaling pathway is also pivotal in the cerebral ischemia neuroprotective actions of melatonin, resveratrol, leptin, and erythropoietin derivatives." (PMID 34943061, 2021). "Beyond erythropoiesis, EPO activity includes neuroprotection in brain ischemia and trauma, endothelial nitric oxide production and cardioprotection, skeletal muscle wound healing, and context dependent bone remodeling affecting bone repair or bone loss." (PMID 34603036, 2021). "GRINA confers neuroprotection and is regulated by erythropoietin (EPO) after murine cerebral ischemia." (PMID 31683519, 2019). "On the one hand HIF target genes include erythropoietin and vascular endothelial growth factor, both of which are neuroprotective and result in reduced infarct size after cerebral ischemia." (PMID 31921851, 2019). "EPO, and a group of its derivatives, are being evaluated as possible neuroprotective agents in cerebral ischemia." (PMID 29438293, 2018). "The protective effect of EPO on renal and cerebral ischemia, separately has been shown in various studies." (PMID 29881418, 2018).
Cerebral ischemia (continued). "Erythropoietin pretreatment improves outcome after brain ischemia by decreasing inflammation and blood glucose stabilization." (PMID 30719249, 2018). "As for the EPO inducing effect on PTPRE, it is interesting to note that another phosphatase, dual-specificity protein phosphatase 5 (Dusp5), was among the few genes induced by EPO in rats with cerebral ischemia, where EPO treatment is protective." (PMID 29123527, 2017). "The increased number of BrdU+ cells in the peri-infarct area indicated that EPO treatment either stimulated proliferation or DNA repair capacity after cerebral ischemia." (PMID 28840056, 2017). "The effect of preserving brain structure and function was also induced by EPO treatment in animals undergoing brain ischemia." (PMID 28848617, 2017). "It has been reported that EPO is a promising acute therapeutic agent for cerebral ischemia in animal studies." (PMID 24587228, 2014). "Erythropoietin (EPO) is a neuroprotective agent against cerebral ischemia/reperfusion (I/R)-induced brain injury." (PMID 24587228, 2014). "We previously reported that the protective activity of EPO in a model of cerebral ischemia was paralleled by an upregulation of synaptic plasticity genes, particularly early growth response 2 (EGR2)." (PMID 24672526, 2014). "The aim of this study was to determine the Neuro-EPO delivery into the central nervous system (CNS) to exert a neuroprotective effect in cerebral ischemia model of the Mongolian gerbil." (PMID 22701364, 2012). "The administration of EPO to animals with experimental cerebral ischemia resulted in the reduction of the local production of TNF-α, IL-6, and the chemokine MCP-1, subsequently leading to a marked reduction of infarct size." (PMID 22567318, 2012). "In a model of cerebral ischemia, EPO treatment reduced BBB leakage, increased the expression of tight junction proteins and reduced the formation of oedemas in the ischemic region." (PMID 22741599, 2012). "Treatment with recombinant human EPO has been reported to stimulate anti-inflammatory signaling, which was suggested to contribute to its direct neuroprotective effect during cerebral ischemia." (PMID 22567318, 2012). "Mechanisms of action of EPO and G-CSF include the reduction of glutamate-induced neuronal cell death and anti-inflammatory effects after cerebral ischemia." (PMID 23109881, 2012). "A possible neuroprotective agent is the rHu-EPO, whose effects have been demonstrated in models of brain ischemia." (PMID 22701364, 2012). "At 7 d post-cerebral ischemia, infarct volumes were significantly smaller in three groups: EPO (10,000 U/kg) + G-CSF (100 μg/kg) in Group F; EPO (5000 U/kg) + G-CSF (50 μg/kg) in Group G; and EPO (2500 U/kg) + G-CSF (50 μg/kg) in Group I." (PMID 20404921, 2010). "Locomotor activities after cerebral ischemia in EPO+G-CSF group were significantly better than those in the other groups." (PMID 20404921, 2010). "Transgenic mice showing cerebal and systemic overexpression of EPO revealed an impaired outcome in a model of focal brain ischemia." (PMID 19079544, 2008). "Therefore, HIF-PH inhibitors hold a clinical use in elevating EPO levels and preventing damage related to ischemia-reperfusion such as cerebral ischemia, cardiac ischemia, and ischemic renal failure." (PMID 35250554, 2022). "Notably, NBO is capable of promoting exogenous erythropoietin (EPO) production, which plays a pivotal role in anti-apoptosis and neuroprotection in patients with cerebral ischemia." (PMID 33281736, 2020). "We investigated whether EPO, hUCBC, and hUCBC+EPO affect neuronal damage after brain ischemia at 21 d post-therapy." (PMID 31024439, 2019). "In addition, EPO has been shown to be neuroprotective, and its induction is believed to have a protective role in cerebral ischemia and after hypoxic reconditioning." (PMID 28195189, 2017). "In CNS diseases, such as brain ischemia, the EpoR connects EPO to JAK2." (PMID 28848617, 2017).